ERBIN (erbb2 interacting protein)
Description:
Acts as an adapter for the receptor ERBB2, in epithelia. By binding the unphosphorylated 'Tyr-1248' of receptor ERBB2, it may contribute to stabilize this unphosphorylated state. Inhibits NOD2-dependent NF-kappa-B signaling and pro-inflammatory cytokine secretion. Acts as a mediator of keratinocyte differentiation by sequestering SHOC2 away from ERK-activating RAS complexes.
Synonyms: ERBB2IP; LAP2; HEL-S-78
Tractability: Small molecule: it has a binding pocket of medium quality. Antibody: UniProt places it where antibodies can reach, with high confidence; its Gene Ontology location is reachable by antibodies, with high confidence; the Human Protein Atlas places it where antibodies can reach. PROTAC: ubiquitination databases record sites on it.
Gene: Protein-coding gene on chromosome 5 (65,883,128 to 66,082,546, forward strand). Ensembl gene ENSG00000112851.
Subcellular location: Cell junction, hemidesmosome; Nucleus membrane; Basolateral cell membrane; Cytoplasm; Cell membrane
Subcellular location (Human Protein Atlas): Cell Junctions; Plasma membrane
Pathways (Reactome):
Disease: Constitutive Signaling by Overexpressed ERBB2; Drug resistance in ERBB2 TMD/JMD mutants; Resistance of ERBB2 KD mutants to AEE788; Resistance of ERBB2 KD mutants to afatinib; Resistance of ERBB2 KD mutants to lapatinib; Resistance of ERBB2 KD mutants to neratinib; Resistance of ERBB2 KD mutants to osimertinib; Resistance of ERBB2 KD mutants to sapitinib; Resistance of ERBB2 KD mutants to tesevatinib; Resistance of ERBB2 KD mutants to trastuzumab; Signaling by ERBB2 ECD mutants; Signaling by ERBB2 KD Mutants; Signaling by ERBB2 TMD/JMD mutants
Signal Transduction: Downregulation of ERBB2 signaling; Drug-mediated inhibition of ERBB2 signaling; RAC1 GTPase cycle; RAC2 GTPase cycle; RAC3 GTPase cycle; RHOA GTPase cycle; RHOB GTPase cycle; RHOC GTPase cycle; RHOG GTPase cycle; Signaling by ERBB2
Gene Ontology:
Molecular function: protein binding; signaling receptor binding; ErbB-2 class receptor binding; structural constituent of cytoskeleton
Biological process: cellular response to tumor necrosis factor; negative regulation of nucleotide-binding oligomerization domain containing 2 signaling pathway; regulation of keratinocyte differentiation; response to lipopolysaccharide; response to muramyl dipeptide; intracellular signal transduction; cytoskeleton organization
Cellular component: basolateral plasma membrane; cell junction; cytoplasm; hemidesmosome; nucleus; plasma membrane; basal plasma membrane; basement membrane; glutamatergic synapse; neuromuscular junction; nuclear membrane; postsynaptic specialization
Genetic constraint (gnomAD): Loss-of-function variants: 31 observed, 79.53 expected, observed/expected ratio (o/e) 0.39, 90% interval 0.29 to 0.53. The upper end of that interval is the gene's LOEUF score, 0.53, which puts it in group 2 of 6, group 1 being the genes least tolerant of losing a copy. Missense variants: 1,104 observed, 1,119.2 expected, observed/expected ratio (o/e) 0.99, 90% interval 0.94 to 1.04. Synonymous variants: 373 observed, 386.08 expected, observed/expected ratio (o/e) 0.97, 90% interval 0.89 to 1.05.
Homologues: Orthologues: chimpanzee ERBIN (97% identical), macaque ERBIN (95% identical), dog ERBIN (93% identical), pig ERBIN (93% identical), mouse Erbin (89% identical), rabbit ERBIN (89% identical), rat Erbin (88% identical), guinea pig ERBIN (88% identical), tropical clawed frog erbin (70% identical), zebrafish erbin (60% identical). Paralogues in human: LRRC7 (42% identical), SCRIB (24% identical), LRRC1 (15% identical), PHLPP1 (14% identical), PHLPP2 (14% identical), MFHAS1 (14% identical), LRRD1 (12% identical), LRRK1 (11% identical), PIDD1 (11% identical), LRRC40 (11% identical), SHOC2 (10% identical), LRRIQ4 (10% identical), and 19 more.
Diseases named in the same sentence as ERBIN in open-access papers:
ERBIN is named in the same sentence as 43 diseases in open-access papers, as found by Europe PMC text mining. Sharing a sentence is not in itself a finding about the gene and the disease. The quoted sentences say what the papers report.
breast cancer (5 papers, 2014 to 2025). A primary or metastatic malignant neoplasm involving the breast. "One protein cluster was enriched with kinase domain-containing proteins, such as Src, ERBB2, and ERBB2IP (ERBIN), reinforcing the idea that p140Cap can associate and regulate kinases implicated in breast cancer transformation and progression." (PMID 34708040, 2021). "The NBCn1 interaction with ERBIN is particularly interesting as ERBIN binds to the ErbB2 receptor tyrosine kinase, a key protein playing a role in breast cancer development and progression." (PMID 24844638, 2014).
Netherton syndrome (4 papers, 2020 to 2025). Netherton syndrome (NS) is a skin disorder characterized by congenital ichthyosiform erythroderma (CIE), a distinctive hair shaft defect (trichorrhexis invaginata; TI) and atopic manifestations. "Instead, other syndromes are now part of the HIES, include Comel- Netherton syndrome, ERBB2-interacting protein (ERBIN) deficiency, IL 6 receptor (IL6R) deficiency, IL6ST deficiency, and Loes- Dietz syndrome." (PMID 35185921, 2022).
colitis (3 papers, 2020 to 2024). Inflammation of the colon. "For instance, decrease in Erbb2 interacting protein (ERBIN) expression in intestinal epithelium led to activation of autophagy and further to activation of colitis state." (PMID 32659925, 2020). "Interestingly, ERBIN expression is decreased in people with IBD, and ERBIN inhibits autophagy and subsequent autophagic cell death in murine models of DSS-induced colitis." (PMID 38622632, 2024).
colorectal cancer (3 papers, 2020 to 2023). A primary or metastatic malignant neoplasm that affects the colon or rectum. "It was identified that circ-ERBIN was elevated in CRC, and it promotes colorectal cancer growth and metastasis by mediating HIF-1α through miR-125a-5p and miR-138-5p, suggesting that circ-ERBIN is a potential target for CRC treatment." (PMID 37587207, 2023). "Given the roles of circ-ERBIN and 4EBP-1 in CRC progression, we studied the roles of miR-125a-5p and miR-138-5p in circ-ERBIN mediated migration and invasion of colorectal cancer cells." (PMID 33225938, 2020).
cardiac hypertrophy (2 papers, 2018 to 2021). "The Erbb2 Interacting Protein (Erbb2ip) is present in relatively high levels in the heart and has been found to be down-regulated in heart biopsies from human failing hearts, with a role in attenuated ERK signaling to negatively modulate cardiac hypertrophy experimentally in mice." (PMID 30241514, 2018). "The expression of ERBB2 interacting protein ERBB2IP (ERBIN), which is important for ERBB2 stabilization and NRG1 signaling and is considered as a negative modulator of pathological cardiac hypertrophy, was expressed in both cell types, and increased in co-culture hiPS-ECs." (PMID 34422835, 2021).
eosinophilic esophagitis (1 paper, 2025). Eosinophilic esophagitis (EoE) is a chronic, allergic disease of the esophagus characterized clinically by symptoms of esophageal dysfunction (including vomiting, dysphagia, feeding disorders, food impaction and abdominal pain) which persist after treatment with proton pump inhibitors (PPIs). "ERBB2-interacting (ERBIN) protein deficiency is characterized by eczema, eosinophilic esophagitis (EoE), recurrent respiratory infections, high IgE levels as well as skeletal and connective tissue abnormalities (i.e., joint hypermobility and vascular abnormalities)." (PMID 39945219, 2025).
eosinophilic gastrointestinal disease (1 paper, 2025). "A heterozygous LOF variant in ERBB2IP, encoding ERBIN, might be responsible for significant eosinophilic gastrointestinal diseases (EGIDs), allergen-specific reactivity, and connective tissue abnormalities." (PMID 39859044, 2025).
heart failure (1 paper, 2021). Inability of the heart to pump blood at an adequate rate to meet tissue metabolic requirements. "Additionally, ErbB2-interacting protein (Erbin) has been identified as an antagonist of RTK Erb2 downstream activity, where null mice exhibit pathological hypertrophy and heart failure following pressure overload." (PMID 33923899, 2021).
lung adenocarcinoma (1 paper, 2025). A carcinoma that arises from the lung and is characterized by the presence of malignant glandular epithelial cells. "Our results show that ERBIN inhibits TGF‐β‐induced EMT in NMuMG breast and in A549 lung adenocarcinoma cell lines." (PMID 40859866, 2025). "Here, we show that ERBIN inhibits TGF‐β‐induced epithelial‐to‐mesenchymal transition in NMuMG breast and A549 lung adenocarcinoma cell lines." (PMID 40859866, 2025).
lung carcinoma (1 paper, 2025). "By performing Kaplan–Meier analysis of breast and lung cancer patient cohorts, we found that low ERBIN expression correlates with worse outcomes." (PMID 40859866, 2025). "In breast and lung cancer patients, low ERBIN expression correlates with poor clinical outcomes." (PMID 40859866, 2025). "To examine ERBIN's effect on TGF‐β‐induced EMT, we analyzed breast and lung cancer patient cohorts and found that ERBIN positively correlates with the epithelial marker CDH1 (encoding E‐Cadherin) and negatively correlates with the mesenchymal markers CDH2 (encoding N‐Cadherin) and SNAI1." (PMID 40859866, 2025).
melanoma (1 paper, 2025). A malignant, usually aggressive tumor composed of atypical, neoplastic melanocytes. "Three ATP2B4–RASGRF2 fusions and two ERBIN–RASGRF2 fusions have been previously reported in melanocytic proliferations (n = 4) and a single melanoma lacking other RAS-activating oncogenic alterations." (PMID 40615519, 2025).
pancreatic cancer (1 paper, 2025). "ERBIN, a scaffold protein that modulates ERBB2 signalling, may further contribute to pancreatic cancer progression." (PMID 40952239, 2025).
tumor (21 papers, 2008 to 2025). "The autologous tumor infiltrating lymphocytes (TILs) that were specific to a mutated antigen ERBB2 interacting protein (ERBB2IP) expressed by the patient’s cancer were harvested and expanded in vitro." (PMID 32748173, 2020). "They first treated a patient with metastatic epithelial cancer via the adoptive transfer of ERBB2 interacting protein (ERBB2IP) mutation–reactive CD4+ TILs to achieve tumor regression in 2014." (PMID 31492199, 2019). "In this study, we found that ERBIN is associated with tumor cell proliferation in MES-GBM." (PMID 38773970, 2024). "Compared with group B, we found that less RASGRP1, VPS28, and RAS downstream proteins p-MEK1/2 and p-ERK1/2 were expressed in mice tumor sections of group G. Moreover, the group G had high levels of ERBIN expression." (PMID 38773970, 2024). "The data showed a positive correlation between circ-ERBIN and 4EBP-1 in circ-ERBIN op or knockdown stable cells and samples from subcutaneous tumor models." (PMID 33225938, 2020). "Collectively, these results demonstrate that circ-ERBIN overexpression promotes CRC tumor growth and progression." (PMID 33225938, 2020). "ERBIN promotes HCC by inactivating ERα‐mediated tumor suppressor signaling." (PMID 39778021, 2025). "Moreover, we found that the TBD0220-KRAS group of tumor-bearing mice had low ERBIN expression levels, but high p-MEK and p-ERK expression levels." (PMID 38773970, 2024). "As indicated, circ-ERBIN overexpression significantly promoted tumor growth in vivo." (PMID 33225938, 2020). "Interestingly, we observed that tumors formed by circ-ERBIN op stable cells grew larger and more quick, suggesting tumor angiogenesis and HIF-1α signaling were up-regulated in these tumors." (PMID 33225938, 2020). "EPIC-0412 treatment inhibited tumor proliferation and EMT progression by upregulating the ERBIN expression both in vitro and in vivo." (PMID 38773970, 2024). "ERBIN overexpression inhibited the RAS signaling and downstream proliferation and invasion effects of GBM tumor cells." (PMID 38773970, 2024). "Taking together, we demonstrate that EPIC can activate ERBIN gene expression by perturbing the HOTAITR-EZH2 interaction, which in turn inhibits the activation of RAS signaling and tumor growth in vitro and in vivo." (PMID 38773970, 2024). "ERBIN interacted with the oncogenic ERBB2 tyrosine kinase receptor and was reported as a promoter of tumor growth by ERBB2 and as a tumor suppressor by negatively regulating both Akt and RAF/MEK/ERK signaling." (PMID 32183175, 2020). "Function-based experiments were performed using circ-ERBIN overexpression and knockdown cell lines in vitro and in vivo, including CCK8, colony formation, EdU assay, transwell, tumor growth and metastasis models." (PMID 33225938, 2020). "We found significant increase in ERBIN expression in DCIS and invasive tumor areas as compared to non-malignant and myoepithelial cells, although the absolute increase appeared greater for DCIS than for invasive tumor." (PMID 40390040, 2025).
cancer (9 papers, 2019 to 2025). A tumor composed of atypical neoplastic, often pleomorphic cells that invade other tissues. "Since we found that ERBIN plays a suppressive role in cancer development, pharmacologically targeting TGF‐β signaling in cancer cells may restore ERBIN expression and inhibit EMT induced by both TGF‐β stimulation and ERBIN downregulation." (PMID 40859866, 2025). "Single-cell transcriptomic profiling of lung metastases from CRC patients uncovered that a special subtype of B cells (ERBIN+) was involved in cancer metastases, and targeting Erbin as well as the combinatory block of B cells and PD1 could suppress lung metastasis of CRC in mice." (PMID 36045190, 2022). "Genetic manipulations of ERBIN expression were complemented by pharmacological manipulation of TGFBR and EGFR, leading to the conclusion that TGFBR and EGFR signaling pathways collaborate to promote EMT in breast and lung (cancer) epithelial cells." (PMID 40859866, 2025).
ERBIN also shares sentences with these, for which no sentence is quoted: cholangiocarcinoma (6 papers); Ehlers-Danlos syndrome (2); hepatocellular carcinoma (2); Loeys-Dietz syndrome (2); PTEN hamartoma tumor syndrome (2); Sepsis (2); abdominal aortic aneurysm (1); anxiety disorder (1); asthma (1); autism (1); autoimmune disease (1); breast invasive carcinoma (1); breast tumor (1); cholesteatoma (1); coronary atherosclerosis (1); depression (1); eczema (1); endometrial cancer (1); endometriosis (1); genetic disorders (1); hyper-IgE syndrome (1); Hypercholesterolemia (1); hypothyroidism (1); inflammation (1); influenza infection (1); intestinal cancer (1); ovarian carcinoma (1); type 2 diabetes (1); virus infections (1).